STAT3 (signal transducer and activator of transcription 3)
Diseases named in the same sentence as STAT3 in open-access papers (continued):
Sharing a sentence is not in itself a finding about the gene and the disease.
cancer (continued). "miR-155 overexpression in cancer cells enhances immune cell influx by increasing the production of chemoattractants via suppressing SOCS1 and tilting the p-STAT1/p-STAT3 balance." (PMID 35925680, 2022). "Through direct binding, minocycline inhibits the kinase activity of LYN, leading to reduced STAT3 activation, thereby represses the EMT and metastasis of cancer cells." (PMID 35414768, 2022). "Based on these findings, STAT3 and NRF1 have been proposed as the most important transcription factors for maintaining the homeostasis of proteasomes in cancer cells." (PMID 35269802, 2022). "In this section, we exclusively analyze how STAT3 promoted carcinogenesis and how STA3 can be pharmaceutically exploited for cancer inhibition." (PMID 35955525, 2022). "Another forkhead box (FOX) reported as important for laryngeal SCC DR is FOXD2-AS1, which acts as a scaffold for STAT3 and PRMT5, promoting STAT3 transcriptional activity, maintaining cancer stemness, and promoting chemotherapeutic resistance." (PMID 35978835, 2022). "HGF/c-Met signaling promoted metastasis of cancer cells by regulating a diverse downstream prometastatic effector molecules, via Ras-MAPK/ERK, PI3K/AKT signaling, JAK2/STAT3 signaling." (PMID 35246503, 2022). "The activation of the JAK/STAT3 and TNFA/NFKB axes was widely reported to induced increased invasive and metastatic ability via enhancing EMT in various cancers." (PMID 36429098, 2022). "Then, STAT3 can homodimerize or heterodimerize with other STAT proteins to translocate to the nucleus and activate the transcription of inflammatory and cancer‐related genes." (PMID 34850540, 2022). "STAT3 enhanced the transcription of apoptosis regulator Mcl-1 and cell cycle regulator cyclin D2 (CCND2) to decrease the sensitivity of cancer cells to radiation, according to more research on the glioma, as well as colorectal cancer." (PMID 36231093, 2022). "Compared with other molecules directly downstream of ALK, such as Smad4, STAT3, PI3K and PLC-γ, TOPK is a better target for cancer therapy." (PMID 36167821, 2022). "Diosgenin appears to be a novel STAT3 activation pathway inhibitor with potential application to treatment of HCC and other cancers." (PMID 36193062, 2022). "Overall, our data highlight the importance of STAT3 signaling in PMEO cytotoxic activity, as well as the possibility of developing adjuvant therapy or sensitizing cancer cells to conventional chemotherapy." (PMID 35956786, 2022). "mPRα knockdown in A549 and PC-9 cells significantly inhibited STAT3 phosphorylation, as well as HIF1α and VEGF protein levels, decreasing cancer cell migration and invasion." (PMID 35123491, 2022). "ω-3 polyunsaturated FAs, on the other hand, improve the anti-cancer effects of GEM by reducing AKT phosphorylation and suppressing NF-kβ and STAT3 activation, thereby arresting cancer cell proliferation." (PMID 36699061, 2022). "Collectively TLM_CFM-F_OSM demonstrated a superior anti-cancer effect, thereby decreasing the protein expression of lamin B2, SOD, STAT3, and NFKB." (PMID 35745729, 2022). "The inhibitors blunt FAK Try-397 auto-phosphorylation and affects downstream signaling pathways including PI3K/AKT, STAT3 and JNK in some cancer cells, and further influence cell viability, proliferation, migration, and immunosuppressive TME." (PMID 36176444, 2022). "Investigation of anti-cancer mechanisms of tubulosine, originally isolated from bark of Pogonopus tubulosus in 1964, identified tubulosine as a potent inhibitor of JAK2/STAT3 signaling through disruption of IL-6/IL-6Rα/gp130 complex formation." (PMID 35371975, 2022).
cancer (continued). "PLK3 inhibits cancer cell growth and suppresses cellular glucose metabolism through the heat shock protein 90 (HSP90)/signal transducer and activator of transcription 3 (STAT3)/hexokinase 2 (HK2) pathways." (PMID 35487956, 2022). "The results found that PSAT1 can be enriched into the classic signaling pathways of cancer such as mTORC1 signaling, MYC targets and JAK STAT3 signaling." (PMID 36105075, 2022). "Our results suggested that Lon-induced Ca2+-dependent cisplatin resistance is involved in chemotherapy-induced cancer stemness, which is consistent with the reported roles of PYK2, SRC, and STAT3/IL-6 in the enrichment of cancer stem cells." (PMID 35296653, 2022). "CaMKIIγ acts as a major molecular switch for regulating the NF-κB, Wnt/β-catenin, Notch, STAT3, and AKT signaling pathways, which are essential for cancer stem-like features in these cancer cells." (PMID 35267623, 2022). "STAT3, known to positively regulate EMT enhances proliferation or reduces apoptosis in various types of cancer thereby promoting cancer progression." (PMID 35642021, 2022). "This cytokine binds to a type I and II receptor, expressed on different cancer cells and myeloid cells, initiating intracellular signals with phosphorylation of SMAD protein and subsequently phosphorylation of STAT3 to regulate cell migration and invasion." (PMID 34727230, 2022). "Unlike Olaparib, which is known to activate STAT3, Niraparib inhibits STAT3 activity in ovarian and PDAC cancer cell lines and patient tumors." (PMID 36324587, 2022). "STAT3 is a STAT family member that has essential roles in embryonic development, cell survival, inflammation, fibrosis, and cancer metastasis." (PMID 35299661, 2022). "Suppressed activation of signal transducer and activator of transcription 3 (STAT3) and ERK1/2 is a vital process in antiproliferation in cancer cells." (PMID 35705962, 2022). "Studies have demonstrated that downstream of STAT3, estrogen‐regulated zinc transporter LIV‐1, miR‐21, IL‐6, HIF, and VEGFR2 can repress E‐cadherin and modulate EMT in many cancers." (PMID 35356799, 2022). "Mechanistic studies suggest a complex role of IL-6 in cancer development, with effects at both local and systemic levels, mainly mediated through the JAK/STAT3 signaling pathways." (PMID 35948877, 2022). "Several in vitro and in vivo studies have validated the potent part played by STAT3 in precancerous physiology of the stomach, implying that STAT3 could be used as a predictive marker for diagnosis of GC, thus inhibiting STAT3 activity with several inhibitory molecules might help to prevent cancer." (PMID 35401182, 2022). "It was found that MBZ inhibited S1P-induced cancer cell growth, and MBZ showed a growth inhibitory effect by regulating the JAK2/STAT3/Bcl-2 pathway." (PMID 36500220, 2022). "Hence, again, targeting the IL-6/STAT3 axis might be a promising outcome in cancers." (PMID 36091805, 2022). "On the one hand, phosphorylation of STAT3 at Tyr705 by tyrosine kinases such as JAK and SRC or at Ser727 by JNK and other MAPKs results in its activation in cancer." (PMID 35145111, 2022). "Meanwhile, in CRC, low expression of miR-637 leads to activation of the Jak/STAT3 signaling pathway through the lncAMPC/miR-637/LIF axis, thereby promoting inflammation and cancer cell migration and invasion." (PMID 36175921, 2022). "Cancer stem cells (CSCs) have been correlated with PDAC aggressiveness, and activation of STAT3 is involved in the regulation of CSC properties." (PMID 35565185, 2022). "Signal transducer and activator of transcription 3 (STAT3) and nuclear factor erythroid 2 related factor-1 (NRF1) play central roles in maintaining the homeostasis of proteasomes in cancer cells." (PMID 35269802, 2022).
cancer (continued). "Based on these data, and the ability of both folinic acid and thymidine to rescue the STAT3-inhibitory effect of pyrimethamine, we wished to determine whether pyrimethamine caused intracellular metabolite shifts that are consistent with DHFR inhibition in STAT3-driven cancer cells." (PMID 34953855, 2022). "For example, curcumin treatment suppresses the STAT3 phosphorylation in SCLCNCI-H446 and NCI-1688 cancer cells and decreases cyclin B1, which promotes cell cycle progression from G2 to M phases and then inhibits cell proliferation." (PMID 36014474, 2022). "In many human cancers including HCC, STAT3 is considered as a strong bona fide candidate promoting tumorigenesis (Khan AQ." (PMID 35401182, 2022). "STAT3 is also involved in the crosstalk between the TME and the immune system, promoting immune evasion of cancer cells." (PMID 36556226, 2022). "STAT3 and STAT5A as well as STAT5B have pleiotropic roles in the body and can act as critical oncogenes that promote many processes involved in cancer development." (PMID 35229974, 2022). "Some of the gene expression data are also in agreement with previous findings that MOR regulates cancer cell proliferation, migration, and EMT formation by using PI3K, Akt, and STAT3 signaling, while B2AR actions on cancer cells involve P38MAPK signaling." (PMID 35568869, 2022). "Functionally, the IL-6/JAK/STAT3 signaling axis promotes proliferation, angiogenesis, EMT, and the cancer stem cell (CSC) subpopulation, while concurrently suppressing the antitumor immune response." (PMID 35371975, 2022). "ROS promotes and interacts with numerous oncogenic signaling pathways, such as the STAT3, MAPK and NF-κB pathways, to favor the development of human cancers." (PMID 34975298, 2022). "Activated STAT-3 triggers EMT, decreasing E-cadherin and increasing vimentin expression, thus inducing proliferation, migration and invasion of cancer cells." (PMID 35703345, 2022). "Specifically, STAT3 and STAT5, the two of the seven members of the STAT protein family, are the most important proteins for cancer progression." (PMID 36151091, 2022). "STAT is one of the most prominent transcriptional factor families in cancers, consisting of seven structurally similar members: STAT1, STAT2, STAT3, STAT4, STAT5a, STAT5b, and STAT6." (PMID 35883021, 2022). "We inferred that LSECtin can also regulate STAT family members STAT1, STAT3, and STAT5A, which have been reported to be closely related with cancer." (PMID 35821222, 2022). "The mechanism of the anti-cancer effects of combined PGG and cisplatin was demonstrated to occur, at least partially, via inhibiting the STAT3/Akt signaling pathway." (PMID 35890129, 2022). "In contrast, phospho‐Stat3, Vegfa, Vegfb and Vegfc were differentially expressed in GK1 stromal cells as well as cancer cells (2nd to 5th rows)." (PMID 35170261, 2022). "However, whether STAT3 inhibition could directly induce immunogenic death of cancer cells and the underlying molecular mechanisms have not been clarified." (PMID 35665592, 2022). "SH2B3 bound to JAK2 and SHP2 to repress JAK2/STAT3 and SHP2/Grb2/PI3K/AKT signaling pathways, respectively, resulting in reduced cancer cell anoikis resistance, proliferation, migration, invasion, and EMT." (PMID 35589677, 2022). "It has been illustrated that synergistic activity of STAT3 and c-JUN were observed in human cancer specimens." (PMID 35955794, 2022). "Processes significantly influenced the development of cancer, including MYC targets V2, DNA repair, IL-6/JAK/STAT3 signaling, and immune response." (PMID 36226251, 2022). "IL22RA1 was positively correlated with STAT1, STAT3, JAK1, PTPN11, IFNA13, IL24, but negatively correlated with IL10 in specific cancers." (PMID 35874683, 2022).
cancer (continued). "Multiple cytokines and chemokines (TNF-α, TGF-β, granulocyte-macrophage colony-stimulating factor (GM-CSF)), as well as transcription factors (AP-1, NF-kB, STAT3, HIF-1α), participate in inflammatory responses during cancer progression." (PMID 36226048, 2022). "Given the roles of STAT3 and Wnt signaling in EMT 49 and the impact of EMT on migration and invasion of cancer cells 49, we evaluated the effect of NCT-80 on the migration and expression of EMT-related markers of NSCLC cells." (PMID 34987637, 2022). "Gln metabolism is able to protect endocrine-related cancer cells against apoptosis and autophagy through the TIGAR and STAT3 signaling pathways." (PMID 36077501, 2022). "The growth of SOCS1 restoration cancer was suppressed with the same efficacy as treatment with the JAK2 inhibitor AG490, which indicated the negative regulation of SOCS in the JAK/STAT3 pathway." (PMID 35356799, 2022). "Signal transducer and activator of transcription 3 (STAT3) is a member of the Janus kinase (JAK)-STAT pathway, which is one of the key pathways contributing to cancer." (PMID 35865518, 2022). "STAT3 and KRAS mutant proteins have been considered anti-cancer targets; however, they are also considered to be clinically “undruggable” intracellular molecules, except for KRAS(G12C)." (PMID 35886918, 2022). "Mechanistically, leptin binds its receptor OB-R in CSCs by promoting activation of the JAK/STAT3, c-Jun, and Akt pathways, thus inducing the transcription of IL-6, TGF-β, and MMP, which drive cancer cell proliferation and invasion." (PMID 35625629, 2022). "FOXD2-AS1 acts as a scaffold for STAT3 and PRMT5, promoting STAT3 transcriptional activity, essential to maintain cancer stemness and promote chemotherapeutic resistance." (PMID 35978835, 2022). "Key regulators in inflammatory processes in cancer include NF-κB, nuclear factor of activated T-cells, hypoxia-inducible factor 1 (HIF-1), and signal transducer and activator of transcription 3 (STAT3)." (PMID 35164043, 2022). "Although STAT3 and SMAD are attractive therapeutic targets for cancer, they have been shown to be notoriously difficult to target with small molecule inhibitors in clinical trials." (PMID 35655269, 2022). "Deregulation of STAT3 is an oncogenic factor that promotes tumorigenesis and epithelial-to-mesenchymal transition (EMT) in various cancers." (PMID 36551576, 2022). "All of these findings together suggested that OPN promoted cancer growth, ROS production, NOX1 expression, and phosphorylation of JAK2/STAT3 in vivo." (PMID 35418176, 2022). "While JAK inhibition remains heavily studied in multiple cancers, the FDA has administered safety warnings against JAK inhibitors underscoring the need to investigate additional approaches to target the IL-6/JAK/STAT3 pathway." (PMID 35371975, 2022). "RNF6 promotes drug resistance through JAK2/STAT3 signaling pathway and RNF6 upregulation can render cells resistant to multiple anti-cancer drugs." (PMID 35369571, 2022). "ITGA5 was known to promote cancer cell migration and invasion through the FAK/STAT3/AKT signaling pathway in TKI-resistant NSCLC." (PMID 36304306, 2022). "NF-ƙB, EGFR, PTEN/PI3K/AKT, Wnt, HIF-1α, STAT3 and AKT/ERK/mTOR signaling pathways are among those being influenced by dysregulation of miR-671 in different cancers." (PMID 36545507, 2022).
cancer (continued). "First, the GSEA analysis revealed that CASZ1 overexpression was related to cancer‐related signaling pathways, including the “Notch signaling,” “transforming growth factor‐beta (TGF‐β) signaling,” “IL6_JAK_STAT3 signaling,” and “EMT signaling”." (PMID 36276925, 2022). "In recent years, the Janus kinase 1/signal transducer and activator of transcription 3 (JAK1/STAT3) and extracellular signal-regulated kinase (ERK) kinase (MEK)/ERK signaling pathways have been widely reported to involve in cancer development." (PMID 35223991, 2022). "ING5 suppresses aggressive phenotypes of various cancer cells via EGFR/PI3K/Akt, IL-6/STAT3, Akt/NF-κB/NF-κB/MMP-9 or IL-6/CXCL12 pathway." (PMID 36425530, 2022). "PD-L1 is expressed on T and B cells, macrophages, and dendritic cells and many studies have shown that the expression of PD-L1 in cancer cells is tightly regulated by multiple oncogenic signaling pathways, including JAK/STAT3." (PMID 36454780, 2022). "Previous studies have demonstrated that STAT3 plays an important role in tumorigenicity and drug resistance and is aberrantly expressed in HNSCC cancer cells." (PMID 35890129, 2022). "The gene of STAT genes was altered in 1,003 (9%) samples; STAT1, STAT2, STAT3, STAT4, STAT5A, STAT5B, andSTAT6 were altered in 2.3%, 1.7%, 2.0%, 2.4%, 1.6%, 1.9%, and 1.9% of the demanded pan-cancer samples." (PMID 36176415, 2022). "This is particularly true when considering the close interaction of STAT3 and NF-κB members in regulating both separately or together the expression of numerous genes (e.g., MMP-1) involved in cancer initiation, metastasis, and resistance to therapies." (PMID 36139106, 2022). "The levels of p-Stat3 are higher in GC tissues than in ANT tissues, in keeping with the increased expression of p-Stat3 in most malignant tumors tested." (PMID 36454780, 2022). "According to reports, Myr inhibits the proliferation of various cancer cells through multiple signaling pathways, including PI3K/AKT, PAK1/MEK/ERK1/2, cyclin D1/PCNA, STAT3 and so on." (PMID 35646711, 2022). "The crosstalk between oncogene and tumor suppressor transcription factors such as NF-kB, STAT3, HIF-1α, and NRF2, is the mechanism of inflammation-driven cancer." (PMID 35967354, 2022). "LMO2-driven activation of STAT3 signaling requires the LDB1 protein and leads to increased expression of an inhibitor of differentiation 1 (ID1), a master regulator of cancer stemness." (PMID 35805116, 2022). "The Gene Set Enrichment Analysis (GSEA) analysis showed that PSAT1 can be enriched into the classic signaling pathways of cancer such as mTORC1 signaling, MYC targets and JAK STAT3." (PMID 36105075, 2022). "Copper-chelating drugs inhibits the expression of PD-L1 by downregulating phosphorylated STAT3, EGFR, AKT and GSK3β and mediates the ubiquitination and degradation of PD-L1 in cancer cells." (PMID 35279217, 2022). "To accomplish the goals, we used previously reported STAT3 inhibitors and members of SLs family, Alantolactone (ALT) and Brevilin A (Brv-A), based on their current effectiveness against multiple cancer cell lines." (PMID 35281907, 2022). "Taken together, constitutive activation of STAT3 regulates the adaptive immune response in the chronic inflammatory TME and mediates immunosuppression in cancers." (PMID 35356799, 2022). "Phosphorylation of STAT3 at Y705 by SRC and JAK leads to transcription of genes involved in cancer progression, including those regulating apoptosis." (PMID 35732128, 2022).